PDCD6 (programmed cell death 6)
Description:
Calcium sensor that plays a key role in processes such as endoplasmic reticulum (ER)-Golgi vesicular transport, endosomal biogenesis or membrane repair. Acts as an adapter that bridges unrelated proteins or stabilizes weak protein-protein complexes in response to calcium: calcium-binding triggers exposure of apolar surface, promoting interaction with different sets of proteins thanks to 3 different hydrophobic pockets, leading to translocation to membranes. Involved in ER-Golgi transport by promoting the association between PDCD6IP and TSG101, thereby bridging together the ESCRT-III and ESCRT-I complexes. Together with PEF1, acts as a calcium-dependent adapter for the BCR(KLHL12) complex, a complex involved in ER-Golgi transport by regulating the size of COPII coats. In response to cytosolic calcium increase, the heterodimer formed with PEF1 interacts with, and bridges together the BCR(KLHL12) complex and SEC31 (SEC31A or SEC31B), promoting monoubiquitination of SEC31 and subsequent collagen export, which is required for neural crest specification. Involved in the regulation of the distribution and function of MCOLN1 in the endosomal pathway. Promotes localization and polymerization of TFG at endoplasmic reticulum exit site. Required for T-cell receptor-, Fas-, and glucocorticoid-induced apoptosis (By similarity). May mediate Ca(2+)-regulated signals along the death pathway: interaction with DAPK1 can accelerate apoptotic cell death by increasing caspase-3 activity. Its role in apoptosis may however be indirect, as suggested by knockout experiments (By similarity). May inhibit KDR/VEGFR2-dependent angiogenesis; the function involves inhibition of VEGF-induced phosphorylation of the Akt signaling pathway. In case of infection by HIV-1 virus, indirectly inhibits HIV-1 production by affecting viral Gag expression and distribution. [Isoform 2]: Has a lower Ca(2+) affinity than isoform 1 (By similarity).
Synonyms: ALG-2; ALG2; PEF1B
Tractability: Small molecule: it has a high-quality binding pocket. Antibody: UniProt places it where antibodies can reach, with high confidence. PROTAC: ubiquitination databases record sites on it; its protein half-life has been measured.
Gene: Protein-coding gene on chromosome 5 (271,621 to 314,974, forward strand). Ensembl gene ENSG00000249915.
Subcellular location: Endoplasmic reticulum membrane; Cytoplasmic vesicle, COPII-coated vesicle membrane; Cytoplasm; Nucleus; Endosome
Subcellular location (Human Protein Atlas): Cytosol; Nucleoplasm
Gene Ontology:
Molecular function: calcium ion binding; calcium-dependent protein binding; identical protein binding; protein binding; protein dimerization activity; protein heterodimerization activity; protein homodimerization activity; protein-macromolecule adaptor activity; protein-membrane adaptor activity; ubiquitin-like ligase-substrate adaptor activity; magnesium ion binding
Biological process: cellular response to heat; COPII vesicle coating; endoplasmic reticulum to Golgi vesicle-mediated transport; intracellular protein transport; negative regulation of phosphatidylinositol 3-kinase/protein kinase B signal transduction; negative regulation of TOR signaling; negative regulation of vascular endothelial growth factor receptor signaling pathway; neural crest cell development; neural crest formation; positive regulation of angiogenesis; positive regulation of apoptotic process; positive regulation of endothelial cell migration; positive regulation of endothelial cell proliferation; positive regulation of protein monoubiquitination; response to calcium ion; vascular endothelial growth factor receptor-2 signaling pathway; apoptotic signaling pathway; apoptotic process
Cellular component: COPII vesicle coat; Cul3-RING ubiquitin ligase complex; cytoplasm; cytoplasmic vesicle; cytosol; endoplasmic reticulum; endoplasmic reticulum exit site; endoplasmic reticulum membrane; endosome; extracellular exosome; nucleoplasm; nucleus; perinuclear region of cytoplasm; ER to Golgi transport vesicle membrane
Genetic constraint (gnomAD): Loss-of-function variants: 7 observed, 15.52 expected, observed/expected ratio (o/e) 0.45, 90% interval 0.26 to 0.85. The upper end of that interval is the gene's LOEUF score, 0.85, which puts it in group 3 of 6, group 1 being the genes least tolerant of losing a copy. Missense variants: 165 observed, 184.41 expected, observed/expected ratio (o/e) 0.89, 90% interval 0.79 to 1.02. Synonymous variants: 67 observed, 74.32 expected, observed/expected ratio (o/e) 0.9, 90% interval 0.74 to 1.11.
Homologues: Orthologues: rabbit PDCD6 (99% identical), mouse Pdcd6 (99% identical), rat Pdcd6 (99% identical), guinea pig PDCD6 (98% identical), pig PDCD6 (98% identical), zebrafish pdcd6 (82% identical), tropical clawed frog pdcd6 (79% identical), Drosophila melanogaster Alg-2 (62% identical), Caenorhabditis elegans M04F3.4 (53% identical). Paralogues in human: CAPN3 (38% identical), CAPN1 (37% identical), CAPN2 (37% identical), CAPN8 (36% identical), CAPN11 (34% identical), CAPN12 (32% identical), CAPN9 (32% identical), CAPN14 (29% identical), CAPN13 (27% identical), CAPNS1 (25% identical), PEF1 (25% identical), CAPNS2 (24% identical), and 8 more.
Diseases named in the same sentence as PDCD6 in open-access papers:
PDCD6 is named in the same sentence as 39 diseases in open-access papers, as found by Europe PMC text mining. Sharing a sentence is not in itself a finding about the gene and the disease. The quoted sentences say what the papers report.
ovarian carcinoma (14 papers, 2012 to 2024). A malignant neoplasm originating from the surface ovarian epithelium. "PDCD6 can induce migration and invasion of tumor cell in ovarian cancer causing unfavorable clinical outcome to patients." (PMID 35503998, 2022). "PDCD6, located oncytoband 5p15.33-p14.1, is known to be involved in apoptosis survival and is implicated in migrationand invasion in ovarian cancers." (PMID 26678268, 2015). "In addition, we analyzed the association between PDCD6 expression, clinical pathological factors and outcome in ovarian cancer patients." (PMID 22369209, 2012). "Among these, two also associated at nominal significance with ovarian cancer (TLR1 and PDCD6), one also associated with lung cancer (POGLUT3) and one associated with each kidney (POGLUT3), and bladder cancer (LAYN)." (PMID 38684708, 2024). "It has been found that miR-124 can affect cell proliferation, cell cycle, apoptosis, migration, and invasion via inhibiting the expression of PDCD6 in ovarian cancer cells." (PMID 32597292, 2020). "PDCD6 expression is up-regulated in lung cancer patients, while reduced PDCD6 expression is observed in gastric cancer, ovarian cancer tissues and cancer cell lines." (PMID 24392146, 2014). "PDCD6 is highly expressed in metastatic ovarian cancer cells and positively regulates cell migration and invasion." (PMID 22369209, 2012). "In the present study, lentiviral vectors-mediated transfection was used to determine effects of PDCD6 expression silencing on metastatic ovarian cancer cell behavior." (PMID 22369209, 2012). "Two hundred twelve epithelial ovarian cancer tissues were analyzed for mRNA expression of PDCD6 using RT-PCR." (PMID 22369209, 2012). "PDCD6 knockdown significantly inhibited migration and invasion of ovarian cancer cells in vitro, supporting the notion that PDCD6 played an important role in ovarian cancer progression." (PMID 22369209, 2012). "To further explore the function of PDCD6 in ovarian cancer, in this study, we investigated the effects of PDCD6 knockdown by short hairpin RNA (shRNA) on cell growth, cell cycle, apoptosis and motility of ovarian cancer cells." (PMID 22369209, 2012). "In summary, PDCD6 was identified and characterized as differentially expressed proteins between ovarian cancer cells with low and high metastatic property by our previous comparative proteomic study." (PMID 22369209, 2012). "Lentiviral vector with shRNA for PDCD6 was used to investigate the effects of PDCD6 knockdown on cell growth, cell cycle, apoptosis and motility in ovarian cancer cells." (PMID 22369209, 2012). "Further studies are needed to more completely elucidate the molecular mechanisms of PDCD6 involve in ovarian cancer progression." (PMID 22369209, 2012). "Our findings suggest that PDCD6 mRNA expression is an independent predictor of ovarian cancer progression free survival." (PMID 22369209, 2012). "Significantly, the level of PDCD6 expression in epithelial ovarian cancer correlates with clinical progression." (PMID 22369209, 2012). "Further studies are needed to more completely elucidate the molecular mechanisms of PDCD6 in ovarian cancer progression." (PMID 22369209, 2012). "PDCD6 expression was found to be upregulated in tumor tissue samples from lung, breast, colon, and ovarian cancers, which suggested that it may be involved in the maintenance of cellular viability." (PMID 38339272, 2024). "Similarly, PDCD6 was overexpressed in metastatic ovarian cancer cells and was able to promote cell migration and invasion." (PMID 33712026, 2021). "The function of PDCD6 in CRC was consistent with previously reported results regarding ovarian cancer, and PDCD6 overexpression has been reported in hepatomas and lung cancer tissue, suggesting that this protein plays an oncogenic role in the progression of these types of tumors." (PMID 32746883, 2020). "Besides, follicle-stimulating hormone (FSH) inhibits ovarian cancer cell apoptosis through the down-regulation of PDCD6." (PMID 32597292, 2020).
ovarian carcinoma (continued). "Recent studies have revealed that PDCD6 overexpression can promote the progression of hepatomas, breast, and ovarian cancer, suggesting that PDCD6 might be involved in the maintenance of cellular viability." (PMID 32746883, 2020). "PDCD6 expression was upregulated in tumor tissue samples from lung, breast, colon cancer, and ovarian cancer, which suggested that PDCD6 might be involved in maintenance of cellular viability." (PMID 29872511, 2018). "The purpose of this study is to further explore the roles of PDCD6 in epithelial ovarian cancer." (PMID 22369209, 2012). "With a comprehensive understanding of PDCD6 regulation and function, we may be able to tell what confounding biology is involved in the relationship between PDCD6 expression and ovarian cancer progression." (PMID 22369209, 2012). "PDCD6 seems to play an important role in ovarian cancer progression and it may be an independent predictor of progression free survival in epithelial ovarian cancer." (PMID 22369209, 2012). "Besides, PDCD6 could mediate the pro-apoptotic activity of cisplatin or TNFα through the downregulation of NF-κB expression in human ovarian carcinoma cells." (PMID 32597292, 2020). "In addition, the previous studies have demonstrated that PDCD6 was functionally redundant, which could also be severed as an important regulator during the tumorigenesis of lung cancer and epithelial ovarian cancer through stimulating cell migration or invasion." (PMID 32597292, 2020). "Among the targets regulated by miR-124, we could isolate at least six genes (PDCD6, ROCK1, SLUG, STAT3, TGF-β, ZEB1) common to several epithelial cancers, including lung, stomach, hepatocellular, breast, and ovarian cancers." (PMID 36362406, 2022).
breast carcinoma (7 papers, 2017 to 2024). "Previous studies have reported that PDCD6 promotes breast cancer growth and metastasis by regulating the cytoskeleton and mediating the proapoptotic activity of cisplatin and TNF-α through the downregulation of NF-κB expression in different biological process." (PMID 32746883, 2020). "As we found, miR-124-3p directly targeted PDCD6 to inhibit metastasis in breast cancer and cooperated with ROCK1 to reduced procession in Ewing Sarcoma." (PMID 31885731, 2019). "Comparison of results obtained using the two approaches suggested three common proteins, including one favorable target, YARS, and two unfavorable targets, KIAA1522 and PDCD6, as the most reliable proteins to predict chemotherapeutic responses in breast cancer." (PMID 33239070, 2020). "Recently, it has been shown that that miR-124-3p attenuated tumor metastasis by inhibiting PDCD6 expression, and that the miR-124-3p/PDCD6 signaling axis could potentially be a therapeutic target for patients with advanced breast cancer." (PMID 29872511, 2018). "Pdcd6 is reported to be a direct target gene of miR-124-3p in breast cancer cells, but this relationship has not been reported in PH." (PMID 33657879, 2021).
hepatocellular carcinoma (6 papers, 2012 to 2025). A malignant tumor that arises from hepatocytes. "For instance, PDCD6 was upregulated in lung cancer, hepatomas and metastatic ovarian cancer, while PDCD6 was decreased in non-small cell lung cancer and gastric cancer." (PMID 35396512, 2022). "Thus, the increased expression of PDCD6 in hepatocellular carcinoma may be limited to the early stages of the disease." (PMID 40365190, 2025). "Furthermore, PDCD6 was found up-regulated in lung cancer and hepatoma tissue compared with normal tissue, also suggesting that PDCD6 beside its known proapoptotic functions may be a player in survival pathways." (PMID 22369209, 2012).
lung carcinoma (6 papers, 2012 to 2024). "However, the expression of GG genotype of PDCD6 has been reported to reduce the risk of lung cancer." (PMID 35503998, 2022). "One study of lung cancer demonstrated that PDCD6 overexpression was indicative of unfavorable prognosis for patients with early stage non-small cell lung cancer or lung adenocarcinoma; the protein may serve as a potential molecular marker for aggressive lung cancer." (PMID 22369209, 2012).
cervical carcinoma (5 papers, 2015 to 2023). A carcinoma arising from either the exocervical squamous epithelium or the endocervical glandular epithelium. "Other targets, PCDC6 and PCDC6IP, are associated with PMID:35396512:MAT2A, which facilitates PDCD6 methylation and promotes cell growth under glucose deprivation in cervical cancer." (PMID 38283897, 2023). "In our study, we demonstrated that MAT2A facilitates PDCD6 methylation that is critical for PDCD6 protein stability maintenance under glucose deficiency, and thereby suppresses cell apoptosis of cervical cancer cells." (PMID 35396512, 2022). "Furthermore, the clinical analysis indicates that the MAT2A protein level is positively associated with the PDCD6 level, and the high level of PDCD6 significantly correlates with poor prognosis and advanced stages of cervical cancer patients." (PMID 35396512, 2022). "MAT2A can promote the growth of cervical cancer cells under glucose deprivation by mediating the methylation of programmed cell death protein 6 (PDCD6)." (PMID 38020920, 2023). "The interaction between MAT2A and programmed cell death protein 6 (PDCD6) in cervical cancer cell lines was detected by immunoprecipitation, immunoblotting and mass spectrometric analysis." (PMID 35396512, 2022). "Twenty-seven tissues of cervical cancer patients were pathologically confirmed as low PDCD6 expression while 40 cases were confirmed as high PDCD6 expression." (PMID 35396512, 2022). "We also explored the effects of MAT2A and PDCD6 on cell viability and apoptosis in cervical cancer cells." (PMID 35396512, 2022). "We conclude that MAT2A facilitates PDCD6 methylation to promote cervical cancer growth under glucose deprivation, suggesting the regulatory role of MAT2A in cellular response to nutrient stress and cervical cancer progression." (PMID 35396512, 2022). "Taken together, our results revealed that MAT2A facilitates methylation of PDCD6 at K90 site to promote cervical cancer growth under glucose deprivation mediated by AMPK activation." (PMID 35396512, 2022). "Physiologically, expression of PDCD6 K90R leads to increased apoptosis and thus suppresses growth of cervical cancer cells under glucose deprivation." (PMID 35396512, 2022). "In line with the results from in vitro study, the further clinical analysis indicates the MAT2A level is positively related to PDCD6 level in cervical cancer tissues." (PMID 35396512, 2022). "Moreover, the protein level of MAT2A and PDCD6 in cervical cancer patients was validated using IHC analyses, and the clinicopathological characteristics were also analyzed." (PMID 35396512, 2022). "Similarly, up-expressed PDCD6 played the role of inhibiting cell growth in cervical carcinoma cells." (PMID 35503998, 2022). "Thus, our findings support an anti-apoptotic role of PDCD6 in cervical cancer cells at glucose deficiency condition and highlight the positive relationship between PDCD6 and MAT2A during cervical cancer development." (PMID 35396512, 2022). "Moreover, Kaplan analysis showed that high levels of PDCD6 expression in cervical cancer specimens were correlated with decreased overall survival and disease-free survival durations of the patients via GEPIA database." (PMID 35396512, 2022). "However, studies focusing on the role of PDCD6 in human cervical cancer are still rare." (PMID 35396512, 2022). "Our study will provide a novel mechanism by which MAT2A facilitates methylation of PDCD6 to promote cervical cancer growth, suggesting that MAT2A and PDCD6 might be the targets for cervical cancer therapy." (PMID 35396512, 2022). "PDCD6 gene expression was higher in cells sensitive to L-OHP, whileexpression of PDS5B, UBL3, MTIF3,XPO4, CASC8, and GTF3A was lower.UBL3 was identified as one of seven genes that predict relapse andsurvival in early-stage cervical carcinoma patients." (PMID 26678268, 2015).
gastric cancer (5 papers, 2011 to 2025). A primary or metastatic malignant neoplasm involving the stomach. "Whereas, low expression levels of PDCD6 was found to be associated with a poor prognosis in gastric cancer." (PMID 33712026, 2021). "Recent studies comparing gastric cancer and normal tissue have identified a number of genetic markers, including diagnostic markers [NF2, INHBA, SFRP4], prognostic markers [CD9, CDH17, PDCD6], and gastric cancer-associated genes [MUC13, CLDN1, Ki67 and CD34]." (PMID 22133303, 2011).
bladder cancer (4 papers, 2018 to 2024). "Three SNPs [rs2344673 (RGS5), rs3756712 (PDCD6), and rs2293347 (EGFR)] were associated with events of bladder cancer death, albeit in different subgroups." (PMID 31681611, 2019). "A serial of studies demonstrate that the onset and progression of bladder cancer are closely associated with multiple gene polymorphisms including CD44, XRCC1, and PDCD6." (PMID 30755233, 2019). "Today, the role of genetic factors in the incidence of bladder cancer has attracted widespread attention and several genes are currently associated with the incidence of bladder cancer, including CD44, CRCC1, and PDCD6." (PMID 30755233, 2019).
liver cancer (4 papers, 2021 to 2025). An epithelial or non-epithelial malignant neoplasm that arises from the liver. "Findings from these experiments demonstrated that high PDCD6 expression markedly enhanced the proliferation, migration, and invasion capabilities of liver cancer cells." (PMID 39156976, 2024). "Programmed Cell Death 6 (PDCD6): Enhances proliferation, migration, and invasion capabilities of liver cancer cells via activation of the AKT pathway, leading to GSK-3β phosphorylation." (PMID 39156976, 2024). "Hence, menthol's ability to decrease PDCD6 expression by the end of the first month, is indicative of its potential to prevent liver cancer formation and progression in DEN-exposed mice." (PMID 40365190, 2025). "Furthermore, research utilizing animal models, particularly in rats, has shown that PDCD6 expression is significantly higher in liver cancer tissues compared to normal liver tissues." (PMID 39156976, 2024). "The recombination of these two types of genes into PDCD6-AHRR may affect the occurrence and development of liver cancer, making it a valuable target for liver cancer research." (PMID 38704528, 2024). "Our study found that the expression level of PDCD6 was upregulated in three liver cancer cells compared to normal liver cell." (PMID 33712026, 2021).